CASP8 (caspase 8)
Diseases named in the same sentence as CASP8 in open-access papers (continued):
Sharing a sentence is not in itself a finding about the gene and the disease.
diabetic retinopathy (1 paper, 2021). "The underlying molecular processes of SST- and PACAP-receptor signaling include the inhibition of proapoptotic molecules (e.g., caspase-3, caspase-8, FasL and calpain-2), meaning that they could be very well suited for reducing the harmful effects of diabetic retinopathy." (PMID 33466261, 2021).
embryonic carcinoma (1 paper, 2020). "The enhancement of RA signaling and RA-induced cell differentiation were induced by the inhibition of not only Casp8 expression in mouse embryonic carcinoma cell line P19 as well as mouse ES cells, but also Fadd expression in ES cells." (PMID 31659279, 2020). "Thus, Caspase-8 suppresses marked activation of RA signaling in not only mouse ES cells but also mouse embryonic carcinoma and human cancer cells." (PMID 31659279, 2020).
endophthalmitis (1 paper, 2021). An infectious process affecting the internal structures of the eye. "Additionally, genes encoding pro- and antiapoptotic/pyroptosis molecules were found to be differentially regulated in MDR-PA-induced endophthalmitis and included upregulation of caspase-1, caspase-4, and caspase-8." (PMID 35046947, 2021).
esophageal adenocarcinoma (1 paper, 2023). A malignant tumor with glandular differentiation arising predominantly from Barrett mucosa in the lower third of the esophagus. "Furthermore, 1.5% CASP8 amplification and 1% mutation occurred in esophageal adenocarcinoma." (PMID 36533709, 2023).
Fulminant hepatitis (1 paper, 2022). Acute hepatitis complicated by acute liver failure with hepatic encephalopathy occurring less than 8 weeks after the onset of jaundice. "In agreement with the abrogation of the CD95-mediated apoptotic signal in these mice, caspase-8 DA or caspase-8 FGLG mice are resistant to fulminant hepatitis induced by injection of the agonistic anti-CD95 antibody Jo2." (PMID 35563744, 2022).
gastrointestinal infection (1 paper, 2022). "In this study, we uncovered that epithelial STAT1 signaling orchestrates Caspase-8-dependent and -independent epithelial cell death during gastrointestinal infection." (PMID 34497340, 2022). "On a molecular level, we uncovered that the transcription factor STAT1 induces gene expression of several key members of central cell death pathways and controls the activation of Caspase-8-dependent and -independent cell death in the intestinal epithelium during gastrointestinal infection." (PMID 34497340, 2022). "Having shown that STAT1 is involved in orchestrating Caspase-8-independent programmed necrosis during infection with the intracellular pathogen Salmonella, we were interested whether this is a widely used host defense mechanism during gastrointestinal infection." (PMID 34497340, 2022). "In summary, these data demonstrated that STAT1 acts upstream of Caspase-8-independent cell death in the colon during the initial phase of gastrointestinal infection, as lack of this transcription factor in Casp8ΔIEC mice was sufficient to block excessive cell death and lethality." (PMID 34497340, 2022).
germinoma (1 paper, 2011). A malignant germ cell tumor arising in the central nervous system. "However, in germinomas, methylation of gene regulatory regions differed little from control samples, whereas YSTs exhibited increased methylation at a large proportion of the loci tested, showing a ‘methylator’ phenotype, including silencing of genes associated with Caspase-8-dependent apoptosis." (PMID 21712824, 2011).
Giardia infections (1 paper, 2023). "In addition, like HSP70, TLR4 could also mediate inhibition of CASP-9 and CASP-8 activation, expanding the HSP70-mediated anti-apoptotic signaling network during Giardia infections." (PMID 36937289, 2023).
gram-negative bacterial infections (1 paper, 2021). Infections caused by bacteria that show up as pink (negative) when treated by the gram-staining method. "Furthermore, CASP8 is a key upstream regulator of the activation of the CASP11-NLRP3 inflammasome, and CASP8 is activated during gram-negative bacterial infections." (PMID 34740613, 2021).
Granuloma (1 paper, 2023). A compact, organized collection of mature mononuclear phagocytes, which may be but is not necessarily accompanied by accessory features such as necrosis. "Imatinib also induces cell death and survival responses, which, via CASP8, may facilitate resolution of pathology and tissue damage associated with granulomas." (PMID 37200402, 2023).
H1N1 virus infection (1 paper, 2025). "H1N1 virus infection dose- and time dependently induced caspase-8 cleavage, which produced an 18- and 43-kDa fragment in LET1 and NL20 cells." (PMID 39811662, 2025).
hemorrhage (1 paper, 2023). Loss of blood from the vascular compartment to the exterior or into nonvascular body space as a result of rupture or severance of the blood vessels. "Collectively, these data confirm that despite its widespread deletion, the vital role of endothelial Caspase-8 is to constitutively guard against small intestinal hemorrhage." (PMID 35871233, 2023).
hepatitis C (1 paper, 2020). "The top five degrees of the potential targets for the YCHD in the treatment of hepatitis C include PIK3CG, CASP3, BCL2, CASP8, and MMP1." (PMID 32050950, 2020). "Furthermore, we can suggest that the mechanism of the YCHD in the treatment of hepatitis C may be related to the induction or activation of CASP3, CASP8, and promotion of hepatocyte apoptosis." (PMID 32050950, 2020).
herpesvirus-infections (1 paper, 2013). "This type of cell death appears to act as a back-up mechanism when apoptosis fails, such as during herpesvirus-infections, where caspase-8 is often blocked by viral proteins." (PMID 23555634, 2013).
Hip dysplasia (1 paper, 2025). The presence of developmental dysplasia of the hip. "Furthermore, elevated levels of caspase-8 have been found in the interface membranes of aseptically loosened total hip implants, but not in control tissues (e.g., from hip dysplasia or mechanical loosening)." (PMID 41252468, 2025).
Hyperammonemia (1 paper, 2025). An increased concentration of ammonia in the blood. "This suggests that RIPK3-dependent necroptosis, as opposed to caspase-8–dependent apoptosis, may be the primary form of cell death induced by hyperammonemia." (PMID 40053595, 2025).
hyperparathyroidism (1 paper, 2025). Hyperfunction of the parathyroid glands resulting in the overproduction of parathyroid hormone. "Hyperexpression of miR-24 inhibits production of parathyroid hormone by binding CDKN1B/p27, CDKN2A/p16, TGFβ1, and CASP8 transcripts, which are involved in the development of hyperparathyroidism." (PMID 40217882, 2025).
hypopharyngeal cancers (1 paper, 2022). Carcinoma, predominantly squamous cell, arising from the epithelial cells of the hypopharynx. "Using previously published data we compared 67 hypopharyngeal cancers to 595 HNSCC from other sites and found no prominent differences in mutational frequency except for CASP8 and HRAS genes." (PMID 35664801, 2022).
infarction (1 paper, 2023). A localised pathological necrosis of tissue resulting from obstruction of the blood supply usually by a thrombus, an embolus, or vascular torsion. "The expression CASP8 and FADD-like apoptosis regulator (cFlip), also known as Cflar, has been shown to be diminished in failing human and murine post-infarction hearts." (PMID 37426668, 2023).
intervertebral disc degeneration (1 paper, 2024). "The analysis revealed through macrogenetic research of intestinal flora that DHJSD may modulate TNF, NF-kappa B, PI3K-Akt, MAPK signaling pathways through CASP8, TNF-α, IL-3, and other crucial proteins to inhibit apoptosis in the nucleus pulposus and treat rat intervertebral disc degeneration." (PMID 39418241, 2024).
keratitis (1 paper, 2022). A corneal disease that is characterized by inflammation of the cornea. "Recently, caspase-8 was involved in Aspergillus fumigatus keratitis being critical in the recruitment of inflammatory cells and the clearance of the fungus." (PMID 36532444, 2022).
laryngeal tumors (1 paper, 2023). "Of those, we found anatomic and genetic differences among tumors, with CASP8 mutations almost solely in the oral cavity and NSD1 predominant in laryngeal tumors." (PMID 37081260, 2023).
LGL leukemia (1 paper, 2025). "Microarray technology has shown that in LGL leukemia, numerous genes related to cytotoxic functions are upregulated, such as granzymes, cathepsin, calpain, perforin, and caspase-8, displaying a specific pattern similar to that observed in activated cytotoxic T cells." (PMID 40699662, 2025).
Lipedema (1 paper, 2022). Disorder of adipose tissue characterized by symmetric and bilateral enlargement of the lower extremities due to abnormal deposition of subcutaneous fat often in obese women. "Further studies are needed to understand whether the most different inflammatory markers between these groups (TNFSF14, CASP8, EN-RAGE, EIF4EBP1, ADA, MCP-1) play a mechanistic role in lipedema development and perpetuation." (PMID 36387874, 2022).
meningitis (1 paper, 2020). A disorder characterized by acute inflammation of the meninges of the brain and/or spinal cord. "However, so far, there are no scientific reports regarding the associations between EGF, ATM, CASP8 and meningitis." (PMID 33031061, 2020). "More significantly, all vital biotargets of calycosin-anti-meningitis were eventually identified, including EGFR, TNF, EGF, ATM, ESR1, CASP8, NGF." (PMID 33031061, 2020). "Markedly, all vital biotargets of calycosin-anti-meningitis are identified, and at least some of new anti-meningitis targets may include EGF, ATM, CASP8." (PMID 33031061, 2020).
mycobacteriosis (1 paper, 2021). "Notably, the proapoptotic role of the TNF-α–caspase-8 axis is not well narrated in piscine mycobacteriosis." (PMID 34987503, 2021).
myopia (1 paper, 2024). "The proapoptotic proteins Bax, Caspase-3, and Caspase-8 were upregulated in the retinas of chicks undergoing form deprivation, whereas the antiapoptotic protein Bcl-2 was downregulated, indicating that retinal cell apoptosis may be an important mechanism in the development of myopia." (PMID 39160465, 2024).
neuroblastic tumor (1 paper, 2006). A group of nervous system tumors which display neuronal differentiation. "CASP8 promoter hypermethylation was studied in a total of 35 neuroblastic tumors and detected in 21 (60%) of these." (PMID 17064406, 2006).
neuroendocrine carcinoma (1 paper, 2025). A malignant neuroendocrine neoplasm composed of cells containing secretory granules that stain positive for NSE and chromogranin. "Most neuroendocrine cancers lack caspase 8 protein expression." (PMID 41413044, 2025).
neuropathy (1 paper, 2024). A disorder affecting the nervous system that manifests with pain, tingling, numbness, and/or muscle weakness. "Specific genes increased in patients withoutlinezolid-associated neuropathy included ATG4C, BAX, and IGF1, while patients onlinezolid who suffered from neuropathy had an increase in AURKB, CASP3, CASP8, CDK1,CDKN1B, CEBPB, NADSYN1, NRF1, GPX7, and SBSN." (PMID 38939039, 2024).
ocular hypertensive (1 paper, 2024). "Western blot analysis testing caspase-8 expression in the isolated astroglia proteins detected some cleavage products in ocular hypertensive samples besides the full-length 55 kDa inactive proenzyme." (PMID 38824526, 2024).
oligodendroglial tumor (1 paper, 2016). Oligodendrogliomas are cerebral tumors that are differentiated from other gliomas on the basis of their unique genetic characteristics and better response to chemotherapy. "The genes found to be most frequently methylated in oligodendroglial tumors were RASSF1A (80.3%), CASP8 (70.5%), and CDKN2A (52.5%)." (PMID 27367901, 2016).
oral cavity cancer (1 paper, 2022). A primary or metastatic malignant neoplasm involving the oral cavity.
osteomyelitis (1 paper, 2025). An acute or chronic inflammation of the bone and its structures due to infection with pyogenic bacteria. "Preclinical models have associated PANoptosis with sterile inflammatory conditions, exemplified by the prevention of chronic recurrent multifocal osteomyelitis in mice through the concurrent deficiency of Caspase-1, Caspase-8, and RIPK3—key PANoptosis components." (PMID 40664640, 2025).
osteonecrosis (1 paper, 2024). A none disease characterized by death of bone tissue due to a lack of blood supply. "In conclusion, EP300, TRAF6, STAT1, JAK1, CASP8, and JAK2 exhibit significant differences in SANFH (spontaneous osteonecrosis of the femoral head)." (PMID 38204239, 2024). "EP300, TRAF6, STAT1, JAK1, CASP8, and JAK2 have exhibited significant differences in SANFH (spontaneous osteonecrosis of the femoral head)." (PMID 38204239, 2024).
Pancytopenia (1 paper, 2024). An abnormal reduction in numbers of all blood cell types (red blood cells, white blood cells, and platelets). "We found that all Casp8−/− mice became sick and developed BM failure within 6-12 days of observation, characterized by pancytopenia and reduced BM cellularity due to significant reduction of HSPCs." (PMID 38637559, 2024). "Furthermore, low dose polyI:C or LPS injections induced pancytopenia, BM failure and loss of HSPCs in Casp8−/− mice but did not do so in WT mice." (PMID 38637559, 2024).
papillary serous cystadenocarcinoma (1 paper, 2021). A malignant cystic serous epithelial neoplasm characterized by the presence of malignant glandular epithelial cells forming papillary structures. "Serum caspase-8 levels were found to be significantly lower in women with papillary serous cystadenocarcinoma (p ˂ 0.001) and ovarian serous cystadenoma (p ˂ 0.05) compared to serum levels of this parameter in healthy women." (PMID 33919909, 2021).
pericarditis (1 paper, 2026). An inflammatory process affecting the pericardium. "Among them, elevated levels of NEU1, GDNF, and LAT increased the risk of pericarditis, whereas higher levels of CASP8, ZFYVE27, and NAPA decreased the risk of pericarditis." (PMID 41674924, 2026).
periodontal disease (1 paper, 2025). "TMB analysis revealed that low TMB correlated with tobacco-related SBS4 and SBS5, whereas high TMB was associated with periodontal disease and mutations in KMT2C, MUC16, and CASP8, as well as the ID-19 signature." (PMID 41154345, 2025).
pneumococcal infection (1 paper, 2021). Infections with bacteria of the species streptococcus pneumoniae. "The noncanonical caspase-8 may also contribute to the NanA-mediated excessive IL-1β production, although further experiments will be required to delineate the role of caspase-8 in IL-1β production upon pneumococcal infection." (PMID 33777832, 2021).
pneumonia (1 paper, 2026). An acute, acute and chronic, or chronic inflammation focally or diffusely affecting the lung parenchyma, caused by an infection in one or both of the lungs (by bacteria, viruses, fungi, or mycoplasma.). "Pathway readouts supported actions on complementary axes (TLR4-IRAK1, STING1-IFN-β, FPR1-AKT, CASP8, and HDAC2-H3K9ac), providing a mechanistic basis for their collective protection against pneumonia." (PMID 41484909, 2026).
pregnancy diseases (1 paper, 2023). "An altered expression of caspase 8 in the placentas of women with different obstetric complications like preterm labor and PE has been reported in past works; although, to our best knowledge, the expression of caspase 5 in the placental tissue has not been evaluated in pregnancy diseases." (PMID 38002326, 2023).
primitive neuroectodermal tumor (1 paper, 2021). A malignant neoplasm that originates in the neuroectoderm. "Previous reports have indicated that supratentorial primitive neuroectodermal tumors (PNET), as well as ATRT manifest an aberrant RASSF1A methylation but not CASP8." (PMID 34771655, 2021).
prion disease (1 paper, 2024). A transmissible disease that is caused by a protein that is able to induce abnormal folding of normal cellular proteins, leading to characteristic spongiform brain changes, which are associated with neuronal loss without an inflammatory response. "Collectively, the synthesis of proinflammatory cytokines by activated microglia, oligomerization of PrPC/Sc on cell surface and activation of caspase-8 defines the involvement of death receptor pathways in the neuropathology of prion diseases." (PMID 38802941, 2024). "Collectively, activation of both caspase-8 and caspase-3 suggest the involvement of death receptor pathways in prion disease." (PMID 38802941, 2024). "Moreover, caspase-3 proteolysis underscores its position downstream of caspase-8 activation, strengthening the involvement of DR pathways in this prion disease." (PMID 38802941, 2024). "Conversely, the deficiency in TRADD and TRAF2 might weaken neuronal and oligodendrocyte cell survival pathways while amplifying TNFα-TNFR1-RIPK1-FADD-caspase-8 mediated cell death pathways, presenting a complex landscape of cellular fate determination in prion disease pathology." (PMID 38802941, 2024).
promyelocytic leukemia (1 paper, 2018). "Taken together, these findings indicate that 23-HUA induces apoptosis in HL-60 human promyelocytic leukemia cells through formation of DISC and caspase-8 activation leading to loss of ΔΨm and caspase-3 activation." (PMID 30551620, 2018).
psoriasis vulgaris (1 paper, 2019). Plaque psoriasis is the most common presentation of psoriasis. "In the single SNP tests, rs6704688 in CASP8 was significantly associated with psoriasis vulgaris (PsV) in Han population of northeastern China (P = 0.0169, P' = 0.0179 under the additive model; P = 0.0126, P' = 0.0149 under the heterozygous model)." (PMID 30906769, 2019).
pulpitis (1 paper, 2021). Inflammation of the dental pulp. "Since CASP9 is involved in cell apoptosis in human dental pulp stem cells from deciduous teeth and also activation of caspase-9 can lead to activation of downstream caspase-8, CASP8 can be therefore assumed to be involved in the signaling pathway of apoptosis in the pathogenesis of pulpitis." (PMID 33777260, 2021).
retinal (1 paper, 2015). "HMGB1 led to the activation of canonical NLRP3 and non-canonical caspase-8 inflammasomes and the processing of IL-1β in retinal IR injury." (PMID 26224068, 2015).
SARS-CoV infection (1 paper, 2023). "Recent reports showed that both Caspase-8–mediated apoptosis and MLKL-driven necroptosis contribute to disease severity following SARS-CoV infection." (PMID 37494451, 2023).
scoliosis (1 paper, 2024). A congenital or acquired spinal deformity characterized by lateral curvature of the spine. "This seems to be the reason why caspase 8 increases the risk of scoliosis." (PMID 38875409, 2024). "Moreover, the levels of caspase 8, T-cell surface glycoprotein CD6 isoform, and leukemia inhibitory factor significantly increased the risk of scoliosis." (PMID 38875409, 2024).
silicosis (1 paper, 2022). Silicosis is a respiratory disease caused by breathing in (inhaling) silica dust. "Taken together, these data demonstrated that Caspase-1/Gsdmd and Caspase-8/Gsdme both mediated IL-1β maturation and secretion in silicosis." (PMID 36459518, 2022). "Furthermore, we found that in addition to Caspase 1, Caspase-8 cleaved IL-1β in silicosis, explaining why Caspase-1-/- mice also suffered from silicosis." (PMID 36459518, 2022). "Therefore, there exists a compensatory mechanism in which Caspase-8 mediates IL-1β maturation in the absence of Caspase-1 activity, explaining why Caspase-1 deficiency failed to protect mice from silicosis." (PMID 36459518, 2022).
spina bifida aperta (1 paper, 2021). "Apoptosis genes like bcl-2 and caspase-8 play a key role in spina bifida aperta development." (PMID 34520395, 2021).